KIF3A (kinesin family member 3A)
Diseases named in the same sentence as KIF3A in open-access papers (continued):
Sharing a sentence is not in itself a finding about the gene and the disease.
breast carcinoma (7 papers, 2016 to 2023). "Taken together, our findings suggest that both SPEN and KIF3A expression are associated with the development of metastasis in HR-negative breast cancers, possibly through their regulation of primary cilia levels and cellular migration." (PMID 28877752, 2017). "The expression of KIF3A was analyzed using the Oncomine microarray database, and KIF3A was found to be increased in breast cancers compared with normal breast tissues." (PMID 28423710, 2017). "For example, KIF3A and KIF3B have been reported to be implicated in oncogenesis and metastasis of breast cancer and renal carcinoma." (PMID 27128470, 2016). "Thus, the significance and mechanism of KIF3A in breast cancer is still unclear." (PMID 28423710, 2017). "RNA interference to KIF3A decreased MMP2 and MMP9 expression, suggesting that KIF3A was required for breast cancer metastasis." (PMID 36188577, 2022). "RFX1 also has a putative binding site at the human kinesin family member 3A (KIF3A) gene promoter, whose inhibition contributed to the suppression of an aggressive form of breast cancer." (PMID 33964962, 2021). "Collectively, our findings suggest that PLCD1 acts as a tumour suppressor, by KIF3A-mediated suppression of ERK1/2/β-catenin/MMP7 signalling, at least in part, in breast cancer." (PMID 28423710, 2017). "In this study, there was a negative correlation between the expression of PLCD1 and KIF3A in breast cancer." (PMID 28423710, 2017). "Therefore, KIF3A was demonstrated to mediate the effect of PLCD1 on ERK1/2/β-catenin/MMP7 signalling, at least in part, in breast cancer." (PMID 28423710, 2017). "Consistently, high KIF3A levels were also correlated with short distant metastasis-free survival in HR-negative breast cancers but not in HR-positive breast cancers, providing additional evidence that primary cilia may be linked to the metastatic process in patients with HR-negative breast cancer." (PMID 28877752, 2017).
prostate carcinoma (7 papers, 2016 to 2024). A carcinoma that arises from epithelial cells of the prostate gland. "As members of the kinesin family have previously been shown to play a role in mediating taxane resistance in prostate cancer, we investigated if the kinesins most implicated in prostate cancer (Eg5 and KIF3a) were involved in our model of hyperglycaemia-induced chemoresistance." (PMID 27754854, 2017). "For example, KIF3A has been demonstrated to stimulate cell proliferation and invasiveness in advanced prostate cancer through its involvement in the Wnt signaling pathway." (PMID 38552217, 2024). "KIF3A promotes cell proliferation and invasion in advanced prostate cancer via the Wnt signaling pathway." (PMID 33150178, 2020). "Furthermore, kinesin family 3A (KIF3A) over-expression in prostate cancer cells induced activation of Wnt/β-catenin pathway, leading to an acceleration of cell migration as well as proliferation of these cells." (PMID 30813560, 2019). "Moreover, that study reported that KIF3A increased DVL2 phosphorylation by CK1 in prostate cancer cells." (PMID 27596264, 2016). "However, a recent study presented contradictory results in which a knockdown of KIF3A reduced Wnt/β-catenin signalling in prostate cancer cells, whereas overexpression of KIF3A promoted it." (PMID 27596264, 2016). "In addition, upregulation of KIF3A promotes cell proliferation and invasion in prostate cancer." (PMID 33150178, 2020).
eczema (6 papers, 2011 to 2026). "This study identified three new genes (OVOL1, ACTL9, KIF3A) that are associated with eczema." (PMID 30402607, 2017). "Interestingly, seven KIF3A SNPs were also significantly associated with other allergic diseases such as allergic rhinitis and eczema (p-values≤0.008 and p-value≤0.023, respectively) in both our discovery Caucasian and African American populations." (PMID 21912604, 2011). "A combined variant pattern in KIF3A and FLG was strongly associated with a generalized eczema phenotype." (PMID 42039188, 2026).
glioma (5 papers, 2017 to 2023). A benign or malignant brain and spinal cord tumor that arises from glial cells (astrocytes, oligodendrocytes, ependymal cells). "Previously, we found that deleting key ciliogenesis genes (e.g., PCM1, KIF3A) enhanced sensitivity of glioma cells to TMZ." (PMID 35359402, 2022). "To test whether the antiproliferative effects of HDAC6 inhibitors are dependent on tumor cell cilia, we generated patient-derived glioma lines devoid of cilia through depletion of ciliogenesis genes ARL13B or KIF3A." (PMID 33915983, 2021).
medulloblastoma (5 papers, 2016 to 2025). A malignant, invasive embryonal neoplasm arising from the cerebellum. "In particular, one of the first reports that studied the function of Kif3a in mouse medulloblastoma showed that constitutively active SMO-driven tumor formation is inhibited by loss of KIF3a." (PMID 26760767, 2016). "Deletion of the KIF3A gene from established medulloblastoma in mice causes cell growth arrest and tumour regression." (PMID 27596264, 2016). "In medulloblastoma-modeled mice driven by the constitutively active Smo transgene (SmoM2), depletion of Kif3a removes primary cilia to block medulloblastoma formation." (PMID 37006607, 2023). "This is in line with previous studies reporting on tumor growth arrest upon KIF3A ablation in medulloblastoma and glioblastoma cells." (PMID 36127323, 2022). "A more recent study confirmed this finding, showing that KIF3a is necessary for medulloblastoma initiation and maintenance and that conditional ablation of Kif3a levels during tumor formation in vivo is followed by tumor regression." (PMID 26760767, 2016). "Notably, exons 10-11 skipping in Kif3a augmented human medulloblastoma cell proliferation by potentiating the transcriptional activity of Gli2." (PMID 40275081, 2025).
Obesity (5 papers, 2009 to 2022). Accumulation of substantial excess body fat. "Cilia on neurons are required for normal energy homeostasis as conditional knockout models of ciliogenesis genes, IFT88 and Kif3A, cause obesity." (PMID 36568981, 2022). "Induced ablation of the kinesin-2 subunit KIF3A or IFT88 throughout the nervous system or in the hypothalamus cause obesity in mice." (PMID 26926121, 2016). "Conditional knockout of IFT88 or Kif3A in neonatal POMC-expressing neurons leads to obesity in adult mice." (PMID 36568981, 2022). "Germline ablation of either Kif3a or Tg737 in adult mice resulted in hyperphagia-induced obesity with elevated serum leptin, insulin, and glucose levels." (PMID 34211092, 2021). "Here we show that inhibition of ciliogenesis in POMC-expressing developing hypothalamic neurons, by depleting ciliogenic genes IFT88 and KIF3A, leads to adulthood obesity in mice." (PMID 33188191, 2020). "In order to better investigate the role of cilia in obesity, Davenport and colleagues produced two additional mouse models, disrupting Kif3a in the neurons of the CNS and in the hypothalamus." (PMID 19439065, 2009). "A recent study showed that inhibition of ciliogenesis in developing POMC neurons, which was realized by depleting Kif3a or Ift88, led to adulthood obesity in mice; these mice showed disruption of axonal projections through impaired lysosomal protein degradation in POMC neurons." (PMID 34211092, 2021). "Moreover, recent studies have shown that inactivation of two ciliary genes Tg737 and Kif3a in adult life leads to obesity and slow-onset cystic kidney disease." (PMID 19439065, 2009). "Interestingly, specific deletion of Kif3a or Tg737 using synapsin 1-cre (Syn1-cre) led to similar results of obesity and leptin resistance, indicating that neuronal primary cilia may play important roles in the regulation of body weight homeostasis." (PMID 34211092, 2021). "Systemic ablation of ciliary genes from neurons using Syn1-cre led to hyperphagic-induced obesity, and the obesity phenotype of both Kif3a-Syn1-KO and Tg737-Syn1-KO mice was reproduced in POMC-specific Kif3a-KO (Kif3a-Pomc-KO) mice." (PMID 34211092, 2021).
glioblastoma (4 papers, 2016 to 2023). The most malignant astrocytic tumor (WHO grade IV). "For instance, disruption of cilia formation in glioblastoma cell lines through knockdown of essential ciliogenesis genes, such as KIF3A or IFT88, had variable effects on tumor growth in vitro and in vivo." (PMID 38188300, 2023).
Hydrocephalus (4 papers, 2017 to 2023). Hydrocephalus is an active distension of the ventricular system of the brain resulting from inadequate passage of CSF from its point of production within the cerebral ventricles to its point of absorption into the systemic circulation. "The absence of adhesion point was also a constant in Id4KO mice and was already reported to be linked to hydrocephalus in other mutants, such as KIF3A-deficient mice." (PMID 33967685, 2021). "For example, defaults in centrosomal protein Cep290 or intraflagellar transport (IFT) components such as Kinesin family member 3a (Kif3a), Ift188 and Ttc21b, impair primary cilia formation/signaling in turn disrupting ependymal cilia and leading to hydrocephalus in mice." (PMID 36859317, 2023). "Moreover, ablation of the embryonic primary cilia by conditional deletion of Kif3a and Ift88 also disrupts ependymal cilia, resulting in postnatal hydrocephalus." (PMID 28931858, 2017).
allergic disease (3 papers, 2011 to 2025). An immune response that occurs following re-exposure to an innocuous antigen, and that requires the presence of existing antibodies against that antigen. "Our results in mice highlight the independent role of KIF3A as a key mechanistic pathway for allergic disease susceptibility and provide insights into the transcriptional regulation of KIF3A as wells as a potential new target for the prevention and treatment of AD." (PMID 32796837, 2020). "Our results highlight the independent role of KIF3A as a key mechanistic pathway for allergic disease pathogenesis and provide insights into the transcriptional regulation of KIF3A." (PMID 32796837, 2020).
atopic dermatitis (3 papers, 2020 to 2024). "The cilium structural gene kinase family member 3A (KIF3A) is required for skin barrier homeostasis, and KIF3A deficiency leads to atopic dermatitis susceptibility." (PMID 39676858, 2024). "Genetic variants in KIF3A are associated with atopic dermatitis (AD)." (PMID 32796837, 2020). "Single nucleotide polymorphisms (SNPs) in the gene encoding kinesin family member 3A, KIF3A, have been associated with atopic dermatitis (AD), a chronic inflammatory skin disorder." (PMID 32796837, 2020).
bladder cancer (3 papers, 2022 to 2025). "In addition, kinesin family member 3a (KIF3A) is elevated in bladder cancer and can cause the occurrence of bladder cancer." (PMID 35821021, 2022). "In bladder cancer, lentiviral transduction of hBM-MSCs to express miR-139-5p resulted in EVs that targeted kinesin family member 3a (KIF3A), activated cyclin-dependent kinase inhibitor 1 (p21), and suppressed tumor progression." (PMID 41254732, 2025). "Kinesin family member 3A stimulates cell proliferation, migration, and invasion of bladder cancer cells in vitro and in vivo." (PMID 38149473, 2023). "Later, the current results pinpointed that miR-139-5p targeted KIF3A and downregulated KIF3A expression to inhibit the malignant features of bladder cancer cells." (PMID 35821021, 2022). "In summary, the miR-139-5p delivered by BMSCs-EVs reduced KIF3A to activate p21, thus limiting the tumorigenesis and metastasis of bladder cancer cells in vivo." (PMID 35821021, 2022). "Then, it has been identified that miR-139-5p delivered by BMSCs-EVs decreased KIF3A expression to activate p21, thereby restraining the malignant behaviors of bladder cancer cells." (PMID 35821021, 2022). "EVs were isolated from BMSCs and co-cultured with T24 or BOY-12E cells with miR-139-5p mimic/inhibitor, oe-KIF3A, and/or si-p21 transfected to study the roles of miR-139-5p/KIF3A/p21 in bladder cancer cell functions." (PMID 35821021, 2022). "At last, in vivo experimental results have shown that BMSCs-derived exosomal miR-139-5p downregulated KIF3A expression to retard the tumorigenesis and metastasis of bladder cancer cells in vivo." (PMID 35821021, 2022). "A prior study has shown that KIF3A can limit p21 expression, and p21 can inhibit the occurrence of bladder cancer." (PMID 35821021, 2022). "Overall, miR-139-5p arrested the malignant potentials of bladder cancer cells through silencing KIF3A." (PMID 35821021, 2022). "Consistently, KIF3A accelerates the malignant capabilities of bladder cancer cells in vivo and in vitro." (PMID 35821021, 2022). "The Kaplan–Meier method revealed that the survival rate of bladder cancer patients in the KIF3A high expression group was lower than that in the KIF3A low expression group." (PMID 35821021, 2022). "At the same time, an adverse correlation was detected between miR-139-5p and KIF3A expression in bladder cancer tissues." (PMID 35821021, 2022). "Altogether, BMSCs-EVs carried miR-139-5p targeted KIF3A to activate p21, thus delaying the occurrence of bladder cancer." (PMID 35821021, 2022). "Existing literature has shown that KIF3A is highly expressed in bladder cancer and can promote the occurrence of bladder cancer." (PMID 35821021, 2022). "miR-139-5p in BMSCs-EVs arrested the tumorigenesis and lung metastasis of bladder cancer cells in vivo by modulation of the KIF3A/p21 axis." (PMID 35821021, 2022). "In summary, the miR-139-5p delivered by BMSCs-EVs decreased KIF3A expression to activate p21, thus limiting the malignant potentials of bladder cancer cells." (PMID 35821021, 2022). "Consequently, this study uncovered that BMSC-EV-miR-139-5p restrained bladder cancer from occurrence through the mediation of KIF3A/p21 axis." (PMID 35821021, 2022). "The results of RT-qPCR detected that KIF3A was elevated in bladder cancer tissues." (PMID 35821021, 2022). "Therefore, this study aims at investigating the molecular mechanism of miR-139-5p delivered by BMSCs-EVs attenuating bladder cancer through the KIF3A/p21 axis." (PMID 35821021, 2022). "Taken together, miR-139-5p delivered by BMSCs-EVs could potentially attenuate the progression of bladder cancer through suppression of KIF3A and activation of p21." (PMID 35821021, 2022). "KIF3A is elevated in bladder cancer and can induce bladder cancer." (PMID 35821021, 2022). "To pinpoint whether miR-139-5p can modulate KIF3A in bladder cancer cells, we first over-expressed miR-139-5p in T24 cells, and silenced miR-139-5p in BOY-12E cells." (PMID 35821021, 2022).
bladder cancer (continued). "Therefore, we examined whether miR-139-5p can affect the development of bladder cancer by targeting KIF3A." (PMID 35821021, 2022).
food allergy (3 papers, 2017 to 2020). Gastrointestinal disturbances, skin eruptions, or shock due to allergic reactions to allergens in food. "We identified two groups of SNPs covering IL5/RAD50 and IL4/KIF3A, which were significantly associated with food allergy." (PMID 29051540, 2017).
Kidney Cyst (3 papers, 2015 to 2026). Abnormal fluid filled sac within the kidney, either acquired or congenital. "Recent studies showed that kidney-specific inactivation of Kif3a produces kidney cysts and renal failure, suggesting that kinesin-mediated intracellular transportation is important for the establishement and maintenance of renal epithelial cell polarity and normal nephron functions." (PMID 25885434, 2015). "Furthermore, it has been shown that KIF3A−/− and KIF3B−/− hPSCs lacking cilia remain pluripotent and self-renewing, but during differentiation they develop defects in neurogenesis, nephrogenesis, and kidney cyst formation." (PMID 41161866, 2026).
lung carcinoma (3 papers, 2016 to 2024). "Thus, we examined the possibility that KIF3A knockdown indirectly affects Wnt/β-catenin signalling through its role in the assembly of primary cilia in lung cancer cells." (PMID 27596264, 2016). "For instance, the KIF3A gene, which encodes the Kinesin family member 3A motor protein, has been associated with carcinogenesis inhibition and apoptosis induction in NSCLC cells, as well as with adverse survival outcomes in lung cancer patients bearing low KIF3A protein expression levels." (PMID 39766023, 2024). "To investigate the role of KIF3A in Wnt pathway regulation in lung cancer, we established A549 and SW900 NSCLC cell lines stably expressing small hairpin RNAs (shRNAs) specific for KIF3A." (PMID 27596264, 2016).
polycystic kidney disease (3 papers, 2010 to 2023). A usually autosomal dominant and less frequently autosomal recessive genetic disorder characterized by the presence of numerous cysts in the kidneys leading to end-stage renal failure. "Later, other ciliary proteins in addition to polaris, such as Kif3a, were also associated with polycystic kidney disease." (PMID 37682373, 2023). "Kif3a and polaris, two proteins previously identified for their implications in polycystic kidney disease, are now known to play key roles in IFT." (PMID 37682373, 2023).
thyroid cancer (3 papers, 2021 to 2025). "Defective ciliogenesis caused by deleting the IFT88 and KIF3A genes from thyroid cancer cell lines increased VDAC1 oligomerization following VDAC1 overexpression, thereby facilitating upregulation of mitochondria-dependent apoptosis." (PMID 33602982, 2021). "Here we established a mouse model with thyrocyte-specific loss of primary cilia (Tg-Cre;Ift88flox/flox) and human thyroid cancer cell lines with ciliary loss by silencing the KIF3A or IFT88 gene." (PMID 33602982, 2021). "Thus, we analyzed the oligomeric status of VDAC1 in KIF3A-deficient or IFT88-deficient thyroid cancer cell lines." (PMID 33602982, 2021). "We found that KD of KIF3A or IFT88 in thyroid cancer cell lines led to increased apoptotic cell death." (PMID 33602982, 2021). "Therefore, we used a confocal laser scanning microscope to examine mitochondrial morphology and the dynamics of KIF3A-deficient thyroid cancer cell lines and negative control siRNA-transfected cells stained with MitoTracker Red." (PMID 33602982, 2021). "In thyroid cancer cell lines, deletion or knockdown of IFT88 and KIF3A impaired ciliogenesis, enhanced VDAC1 oligomerization following VDAC1 overexpression, and disrupted mitochondrial morphology and function, ultimately promoting mitochondria-mediated apoptosis." (PMID 40389989, 2025). "Notably, the depletion of IFT88 and kinesin family member 3A (KIF3A) enhanced voltage dependent anion channel 1 (VDAC1) oligomerization, thereby promoting mitochondrial-dependent apoptotic cell death in differentiated thyroid cancers." (PMID 40017656, 2025).
basal cell carcinoma (2 papers, 2016). A carcinoma involving the basal cells. "For example, in basal cell carcinoma, loss of Kif3a and cilia has been reported to accelerate Gli2-activated tumor growth." (PMID 26760767, 2016). "Conditional deletion of KIF3A or IFT88 in basal cell carcinoma leads to ciliary elimination and strong inhibition of tumorigenesis induced by mutant SMO." (PMID 27793025, 2016). "A similar observation was reported in basal cell carcinoma in mice, whereby conditional ablation of Kif3a blocked hedgehog-driven tumorigenesis." (PMID 26760767, 2016).
osteosarcoma (2 papers, 2009 to 2020). A usually aggressive malignant bone-forming mesenchymal neoplasm, predominantly affecting adolescents and young adults. "First, we examined the mRNA expression levels of KIF5B in three cancer cell lines(MCF-7, HeLa and U2OS osteosarcoma) and found it to be highly expressed in allthree cell lines when compared to other N-kinesins including KIF5A/KIF5C(Kinesin 1), KIF3A (Kinesin 2) and KIF1A (Kinesin 3)." (PMID 19242560, 2009).